POLE (DNA polymerase epsilon, catalytic subunit)
Diseases named in the same sentence as POLE in open-access papers (continued):
Sharing a sentence is not in itself a finding about the gene and the disease.
ovarian carcinoma (20 papers, 2017 to 2025). A malignant neoplasm originating from the surface ovarian epithelium. "The ovarian cancer group has a small sample size: of these, 62.5% of the POLE variants occurred in POLE ExoD signature sequence contexts." (PMID 38282550, 2024). "Such mutations in POLE are often observed in cases of synchronous endometrial and ovarian carcinomas." (PMID 38136334, 2023). "Pathogenic/likely pathogenic variants in the POLE exonuclease domain were detected in one case (0.12%) of cervical cancer and three cases (0.19%) of ovarian cancer." (PMID 38201563, 2023). "Five female POLE ED variant heterozygotes developed ovarian cancer (OC) between the ages of 33 and 45, including one with bilateral disease age 40 years, but no OCs were found in POLD1 ED variant heterozygotes (Fisher’s exact test, p = 0.31))." (PMID 33948826, 2022). "It has been reported that high frequent POLE mutations are associated with metastatic tumors in synchronous endometrial and ovarian carcinoma." (PMID 36313640, 2022). "The mutations p.Asp95Asn in NBN and p.Lys425Arg in POLE segregated with both breast and ovarian cancer cases; the VUS in MSH6 p.Ser144Ile was identified in the two cases of breast cancer, one of them bilateral, in an HNPCC family." (PMID 32522261, 2020). "Two out of the four variants (NBN p.Asp95Asn and POLE p.Lys425Arg) were also detected in her sister, who developed ovarian cancer." (PMID 32522261, 2020). "Specifically, the POLE p.S459F hotspot mutation was found in samples of endometrioid endometrial carcinoma from patients with synchronous endometrioid endometrial and ovarian carcinomas, which generally have a better prognosis compared with individual occurrences of these cancers independently." (PMID 38136334, 2023). "Notably, POLE mutations are frequently observed in synchronous endometrial and ovarian carcinomas." (PMID 38136334, 2023). "Several oncogenes frequently mutated in endometrial and ovarian cancer (ARID1B, ATM, BRCA1, CHD2, POLE, and PMS2) were also present in LMS." (PMID 39691991, 2025). "Pathogenic mutations in the POLE exonuclease domain were associated with high TMB, and the mutation ratio was low in both cervical and ovarian cancers." (PMID 38201563, 2023). "POLE/POLD1 germline mutation is a predisposing factor for CRC, EC, ovarian cancer, and brain tumors." (PMID 35780178, 2022). "There has been at least one case of ovarian cancer in a family with polymerase proofreading‐associated polyposis (PPAP) caused by a germline POLE PV, but the MSI status of the ovarian tumor was not known or reported." (PMID 33369189, 2021). "In other tumor types, such as lung and ovarian cancer a high mutational burden has a survival advantage in non-ICI treated patients, but in both instances has been attributed to DNA-repair deficiency primarily via BRCA1, BRCA2, or POLE genes." (PMID 29743104, 2018).
colorectal adenoma (18 papers, 2013 to 2024). An adenoma that arises from the colon or rectum. "These germline POLE mutations include the highly penetrant POLE-L424V variant, which predisposes to multiple colorectal adenomas and carcinomas." (PMID 37891003, 2024). "POLE mutation carriers, however, show lower colorectal adenoma rates than MUTYH biallelic mutation carriers who generally only show 2-4 fold increased mutation rates." (PMID 35803914, 2022). "Crypt-like structures from six colorectal adenomas and one carcinoma from individuals with germline POLE or POLD1 mutations were also microdissected and sequenced." (PMID 34594041, 2021). "As reported by previous studies, the POLE p.Leu424Val mutation frequency in multiple colorectal adenomas or familial CRC cohorts seems to be typically ≤ 0.3%, whereas the POLD1 p.Ser478Asn mutation seems to be even less frequent (< 0.1%)." (PMID 28423643, 2017). "We recently identified specific germline EDMs in POLD1 and POLE that are causative for the development of multiple colorectal adenomas and CRC." (PMID 24583393, 2014). "Moreover, missense mutations in the polymerase genes POLE have been identified as rare cause of multiple colorectal adenomas and carcinomas in another recent study." (PMID 29871594, 2018). "A decade ago, germline variants in the proofreading domain of POLE and POLD1 were found to predispose to colorectal adenomas and carcinomas, defining a new tumor syndrome, polymerase proofreading-associated polyposis (PPAP)." (PMID 37990341, 2023). "Germline mutations affecting the exonuclease domains of POLE and POLD1 predispose to colorectal adenomas and carcinoma." (PMID 30827058, 2019). "The recently discovered germ-line mutations in POLE and POLD1 genes from individuals with multiple colorectal adenomas, carcinoma, or both are excellent examples in support of above assumption." (PMID 31226964, 2019). "There are also some reports of WGS being successfully used to implicate rare, high-penetrance germline variants in cancer, for example POT1 mutations in familial melanoma and POLE and POLD1 mutations in colorectal adenomas and carcinomas." (PMID 31614935, 2019). "We have recently shown that germline exonuclease domain mutations (EDMs) of POLE and POLD1 confer a high risk of multiple colorectal adenomas and carcinoma (CRC)." (PMID 23447401, 2013). "There are several reports of WGS being successfully implemented to implicate rare, high-penetrance germline variants in cancer, for example POT1 mutations in familial melanoma and Hodgkin lymphoma and POLE and POLD1 mutations in colorectal adenomas or carcinomas." (PMID 32211398, 2020). "Recently, we identified germline exonuclease domain mutations (EDMs) in human POLD1 and POLE that predispose to ‘polymerase proofreading associated polyposis’ (PPAP), a disease characterised by multiple colorectal adenomas and carcinoma, with high penetrance and dominant inheritance." (PMID 24583393, 2014). "In addition to somatic defects, germline POLE mutations were found in patients with hereditary CRC, with strong evidence for the causative role of a highly penetrant POLE-L424V variant predisposing to multiple colorectal adenomas and carcinomas." (PMID 29352080, 2018).
mismatch repair deficiency (17 papers, 2018 to 2025). "The tumor with mismatch repair deficiency (dMMR) and POLE gene mutations exhibit higher TMB, with a further increase when both the MMR and POLE genes are mutated." (PMID 38287125, 2024). "When feasible, examination of the mutational signature should demonstrate a signature consistent with mismatch repair deficiency and also POLE proofreading domain deficiency for those with accompanying POLE mutation." (PMID 38079020, 2023). "POLE proofreading mutations (POLEm) and mismatch repair deficiency (MMRd) lead to high numbers of DNA replication errors and high mutation frequency." (PMID 33816285, 2021). "This study aims to evaluate potential predictive biomarkers for anti-PD-1/PD-L1 therapy in addition to POLE mutation (POLEm) and MMR deficiency (MMRd)." (PMID 33816285, 2021). "We next turned our attention to the 15 samples with paired POLE exonuclease domain mutation and mismatch repair deficiency (POLE-MSI)." (PMID 29717118, 2018). "However, a recent analysis of tumors from children with biallelic germline MMR deficiency (bMMRD) revealed a subset of tumors with remarkably high mutation burdens (>250 mutations/Mb) that also had a somatic mutation in POLE or POLD18." (PMID 29717118, 2018). "Some mutational processes can lead to high TMB, such as POLE/POLD1 mutation, mismatch repair deficiency, UV light, tobacco smoking, AID/APOBEC activation." (PMID 35935970, 2022). "As expected, the main genetic syndrome identified in both groups was LS but two other syndromes were identified in the unusual MMR-D group: one polymerase E (POLE) deficiency and one CMMR-D (constitutional mismatch repair deficiency)." (PMID 34545179, 2022). "EC can be split into four molecular subtypes, including hypermutated cases with POLE mutations and 25–30% harboring a microsatellite instability (MSI) phenotype with mismatch repair deficiency (dMMR)." (PMID 34199461, 2021). "This suggests that the POLE/POLD1 proofreading defect was present in all cancer cells, and therefore, present in the same cells as the MMR deficiency." (PMID 29717118, 2018). "In addition to the biallelic germline mutations in an MMR gene causing mismatch repair deficiency, these childhood tumors arising in the setting of CMMRD often acquire mutations in the proofreading domain of DNA polymerase epsilon (POLE) or delta (POLD1)." (PMID 38079020, 2023).
mismatch repair deficiency (continued). "Surprisingly, we noted that 3/5 of these cases displayed MLH1 silencing as the likely mechanism of mismatch repair deficiency, suggesting that even when POLE-exo* precedes acquisition of MSI, loss of MMR function is not always due to POLE-mediated mutagenesis of an MMR gene." (PMID 29717118, 2018).
endometrial tumors (15 papers, 2014 to 2024). "Germline pathogenic variants in the exonuclease domain of the replicative DNA polymerase Pol ε encoded by the POLE gene, predispose essentially to colorectal and endometrial tumors by inducing an ultramutator phenotype." (PMID 37891003, 2024). "The current level of evidence is too scarce to draw any conclusions regarding the role of nodal disease in patients with POLE mutation, and further studies are needed to demonstrate any correlation between conventional risk factors and molecular/genomic characterization of endometrial tumors." (PMID 39335173, 2024). "In addition, endometrial tumors with DHODH overexpression also show an increase in mutated POLE and POLD1 genes (* p < 0.5)." (PMID 38136273, 2023). "Interestingly, 72% and 73% of endometrial tumors with DHODH overexpression co-occurrence with a POLE and POLD1 mutation are significantly associated with high-grade tumor stages, respectively (** p < 0.01, **** p < 0.0001)." (PMID 38136273, 2023). "Notably, PolE-associated endometrial tumors also show upregulation of the T-follicular helper genes, CXCL13 and CXCR5, which were recently shown to be powerfully predictive of a positive outcome in CRC." (PMID 35326618, 2022). "This may explain the results from other studies showing that POLE mutations are more frequently detected in high-grade endometrial tumors compared with low-grade tumors." (PMID 36313640, 2022). "Comprehensive examination of the timing of pathogenic somatic POLE mutations in sporadic endometrial tumors by whole genome sequencing confirmed that pathogenic somatic POLE mutations occurred early, and are possibly initiating events in endometrial and colorectal tumorigenesis." (PMID 34944963, 2021). "Additionally, we observed a mutationalsignature similar to the COSMIC signature 10, a higher mutation rate in thistumor than in endometrial tumors with heterozygous POLE-exo*,and an increased number of T lymphocytes." (PMID 33001133, 2020). "In contrast, our data show that patients with DHODH overexpression and wild-type copies of POLE and POLD1 are significantly associated with low-grade (G1 and G2) endometrial tumors (** p < 0.01, **** p < 0.0001)." (PMID 38136273, 2023). "Furthermore, our study may provide a foundation to accurately classify grade III endometrial tumors based on DHODH overexpression associated with the POLE and POLD1 mutation, which may contribute to the better selection of patients for future therapeutic strategies." (PMID 38136273, 2023). "In another study, PolE-mutant endometrial tumors were shown to have the highest expression of immune-associated genes in comparison to MSI and MSS tumors." (PMID 35326618, 2022). "Our study was initiated before the description of the immunogenicity of neoantigens, but their value has been definitely described in POLE-mutated and MSI endometrial tumors." (PMID 27618037, 2016).
glioma (15 papers, 2019 to 2026). A benign or malignant brain and spinal cord tumor that arises from glial cells (astrocytes, oligodendrocytes, ependymal cells). "Rare heterozygous POLE/POLD1 missense variants predicted to be deleterious were identified in glioma patients from 10 (16%) families, co-segregating with the tumor phenotype in families with available DNA from several tumor patients." (PMID 37990341, 2023). "A mean TMB of 13.9 mutations per megabase (mut/Mb) was identified in 14 glioma DNAs from 10 patients with rare POLE/POLD1 variants, with each TMB value higher than 2.6 mut/Mb, the median TMB in a study of 10,294 gliomas." (PMID 37990341, 2023). "While six of the nine different POLE and POLD1 germline missense variants identified here in glioma patients affect amino acids located within or close to the exonuclease domain, three variants affect amino acids in other parts of POLE." (PMID 37990341, 2023). "The somatic POLE mutations can lead to a genomically, histologically and clinically distinct subgroup of high-grade gliomas that are associated with a longer progression-free survival." (PMID 31864301, 2019). "The POLE variant was verified to be heterozygous by targeted sequencing in both glioma patients." (PMID 37990341, 2023). "Consistent with our finding of enlarged nuclei or multinucleated cells in 6/15 (40%) gliomas from patients with POLE/POLD1 germline variants, multinucleated giant or bizarre cells, features of giant cell glioblastoma, were previously observed in high-grade gliomas harboring somatic POLE variants." (PMID 37990341, 2023). "As defects in polymerase proofreading have been associated with the formation of multinucleated giant cells, hematoxylin and eosin stained sections of 15 gliomas from 11 patients with rare POLE/POLD1 variants were evaluated by an experienced neuropathologist (CH)." (PMID 37990341, 2023). "Thus, the brain tumors in POLE/POLD1 variant carriers with a definitive diagnosis were gliomas or medulloblastomas." (PMID 37990341, 2023). "Data compiled here suggest that glioma patients carrying POLE/POLD1 variants may be recognized by cutaneous manifestations, e.g. café-au-lait macules, and benefit from surveillance colonoscopy." (PMID 37990341, 2023). "Our data provide evidence that rare POLE/POLD1 germline variants predispose to gliomas that may be susceptible to ICIs." (PMID 37990341, 2023). "Features of defective polymerase proofreading in most gliomas from patients carrying POLE/POLD1 variants suggest that these tumors may be susceptible to ICIs." (PMID 37990341, 2023). "Therefore, all POLE/POLD1 germline variant carriers with gliomas showing features of defective polymerase proofreading, i.e. 87% of gliomas analyzed here, may benefit from immunotherapy." (PMID 37990341, 2023). "The genes implicated in glioma risk play roles in DNA damage response, e.g., ATM, BRCA2, PMS2, POLE, or diverse other processes including metabolism, signal transduction, and cell cycle regulation." (PMID 41546701, 2026). "Intrinsic tumor factors play a big role, with low TMB and consequent neoantigen paucity making most gliomas immunogenic except in hypermutated cases like bMMRD or POLE-mutant gliomas." (PMID 41583467, 2025). "In 13/15 (87%) gliomas from patients carrying POLE/POLD1 variants, features of defective polymerase proofreading, e.g. hypermutation, POLE/POLD1-associated mutational signatures, multinucleated cells, and increased intratumoral T cell response, were observed." (PMID 37990341, 2023). "In this study, we highlight the role of rare heterozygous germline variants in POLE and POLD1 in glioma predisposition and the risk of developing spinal metastases." (PMID 37990341, 2023). "Six of 10 (60%) families carrying POLE/POLD1 variants had at least two family members with brain tumors, with gliomas occurring together with meningiomas in two families." (PMID 37990341, 2023).
glioma (continued). "Our data provide evidence that deleterious POLE and POLD1 germline missense variants predispose to gliomas, which should be considered a part of the PPAP tumor spectrum, and increase the risk of spinal metastasis development." (PMID 37990341, 2023). "While DNA mismatch repair (MMR) deficiency-associated mutational signatures SBS6, SBS15, SBS21, or SBS26 were identified in 13 of 14 (93%) glioma DNAs from 10 patients with rare POLE/POLD1 variants, a substantial (> 50%) contribution was detected in only 5 of 14 (36%) gliomas." (PMID 37990341, 2023). "While it was our intention to model POLE deficiency in glioblastoma cells by generating a POLE knockout LN-229 clone, this cell clone is not an ideal model for the heterozygous POLE missense variants detected here in glioma patients." (PMID 37990341, 2023). "In the CNS LS-related tumor group, 6 glioma samples (PLS041, PLS046, PLS124, PLS143, PLS185, PLS228) had a TMB greater than 300 but were MSS, and we found each patient harboring mutations in the DNA polymerase genes, POLE or POLD1, which are associated with a hypermutated phenotype." (PMID 41261115, 2025). "Taken together, seven different rare POLE and two different rare POLD1 variants, heterozygous and predicted to be deleterious, were detected in WES datasets of leukocyte DNA of a total of 11 glioma patients from 10 of 61 (16%) tumor families, including the glioma patients from family Fam011." (PMID 37990341, 2023). "However, brain tumor surveillance may be considered in all (adult) patients with digenic inheritance of an MMR gene PV and POLD1 or POLE PV, as high-grade gliomas have been found in patients with LS and PPAP." (PMID 36291559, 2022). "While two of the six gliomas with mutational signatures SBS10/SBS20 were from carriers of POLE variants located within or close to the exonuclease domain, four gliomas harbored POLE non-exonuclease domain variants." (PMID 37990341, 2023). "A comprehensive analysis of hypermutation in human cancer by the IRRDC has defined two subgroups of dMMR gliomas, with an average TMB of 380 mutation/MB and 80 mutation/MB according to the presence or absence of a secondary POLE mutation on top of the primary MMR mutation, respectively." (PMID 38339779, 2024).